FOXO1 (forkhead box O1)
Diseases named in the same sentence as FOXO1 in open-access papers (continued):
Sharing a sentence is not in itself a finding about the gene and the disease.
liver fibrosis (continued). "Additionally, berberine has been shown to inhibit the phosphorylation of forkhead box O1 (FoxO1) and Akt in rats with bile duct ligation-induced liver fibrosis and in HSCs, further supporting its potential as a treatment for liver fibrosis." (PMID 40487380, 2025). "Recent literature reported that targeting PI3K/FoxO1 alleviated liver fibrosis." (PMID 39382800, 2024). "Since FoxO1 plays a critical role in fibrosis and could be O-GlcNAcylated, it is essential to elucidate the role of FoxO1 O-GlcNAacylation on liver fibrosis through gene knockdown." (PMID 36429065, 2022). "Besides the TGF/SMAD pathway, the phosphoinositide 3-kinase/protein kinase C/forkhead box protein O1 (PI3K/Akt/FoxO1) pathway is also a key modulator for liver fibrosis in NAFLD." (PMID 34356308, 2021). "RT-qPCR analysis revealed that FOXO1 expression was reduced in hepatic fibrosis." (PMID 34867446, 2021). "In summary, these suggest that abnormal expression of FOXO1 may be associated with miR-183-5p and TGF-β signaling pathway, influencing the occurrence and development of hepatic fibrosis." (PMID 34867446, 2021). "Next, we used lentivirus to overexpress FOXO1 in LX-2 cells, and we found that overexpression of FOXO1 reversed the promotion of miR-183-5p on liver fibrosis, reducing the fibrotic biomarker levels inLX-2 cells, inhibitingLX-2 cell proliferation, and promoting apoptosis." (PMID 34867446, 2021). "Furthermore, miR-183-5p was found to regulate liver fibrosis through the direct modulation of fork head box protein O1 (FOXO1) and overexpression of FOXO1 prevented TGF-β pathway in LX-2 cells." (PMID 34867446, 2021). "In conclusion, the findings showed thatmiR-183-5p might act as a key regulator of liver fibrosis, and miR-183-5p could promote cholestatic liver fibrosis by inhibiting FOXO1 expression through the TGF-β signaling pathway." (PMID 34867446, 2021). "FOXO1 plays a crucial role in the transdifferentiation and proliferation of HSCs in liver fibrosis." (PMID 29416678, 2018). "As Foxo1 signaling can be activated under acute/chronic liver inflammation, we subsequently explored whether Foxo1 influenced inflammatory response and mitochondrial function in liver fibrosis." (PMID 41424862, 2026). "Thus, it is crucial to investigate whether macrophage-specific Foxo1 signaling contributes to liver fibrosis processes potentially through distinct or complementary pathways." (PMID 41424862, 2026). "Nevertheless, targeting Foxo1 signaling could be a promising strategy for treating liver fibrosis." (PMID 40479577, 2025). "Therefore, targeting key nodes within the macrophage metabolic-signaling network—such as PPARγ/CD36, Foxo1 phosphorylation, mitophagy, and glycolytic enzymes—may offer multi-mechanism therapeutic strategies for liver fibrosis." (PMID 41459510, 2025). "Paeoniflorin could reduce cholestatic inflammation and liver fibrosis in the PBC mouse model by eliminating mtROS through the SIRT1/forkhead box O1 (FOXO1)/superoxide dismutase 2 (SOD2) signaling pathway, and thereby alleviate mitochondrial damage and inhibit NLRP3 inflammasome activation." (PMID 36969233, 2023). "To explore the exact mechanism of Sal B causing the changes of metabolites by FoxO signaling pathway, we also introduced AMP-activated protein kinase (AMPK), an upstream modulator of FoxO1 activity, could inhibit the progression of liver fibrosis by activating its downstream targets such as FoxO1." (PMID 35984595, 2023). "Consequently, we inferred that FOXO1 is involved in liver fibrosis induced by miR-183-5p." (PMID 34867446, 2021). "Ghr treatment reduced ductular reaction and hepatic fibrosis in Mdr2KO mice, regulating cholangiocyte proliferation via GHS-R1a, a G-protein coupled receptor which causes increased intracellular Ca2+ and activation of AMPK and FOXO1, maintaining a low rate of cholangiocyte proliferation." (PMID 32994489, 2020).
liver fibrosis (continued). "FOXO1, which can be regulated by the PI3K/AKT signaling pathway, also plays a crucial role in the trans-differentiation and proliferation of HSCs in liver fibrosis." (PMID 41601875, 2026). "Compared with the WT mice, the Foxo1/YAPM-DKO mice exhibited significantly increased serum ALT levels, liver fibrosis, and mRNA levels of αSMA, Col1α1, TGF-β1, CCL2, and TIMP1 in the HFD-challenged livers." (PMID 39122845, 2024). "Activation of FoxO1 increases TGF-β1 levels, impairing glucose and energy metabolism as well as exacerbating CCL4-induced liver fibrosis." (PMID 37960324, 2023). "For example, miR-182 inhibits FOXO1 expression through the PI3K/AKT signaling pathway, thus aggravating schistosomiasis-mediated liver fibrosis." (PMID 34867446, 2021). "Dietary BA alleviated liver fibrosis induced by a high starch diet to steatohepatitis/recovery symptom via improving glucose and lipid metabolism which regulated by AKT/FOXO1 and cAMP/AMPK/SREBP1 pathway." (PMID 31824338, 2019). "Moreover, Foxo1 induces profibrotic cytokine, TGF‐β1, in macrophages, activating HSCs and driving excess ECM accumulation, eventually contributing to liver fibrosis." (PMID 40479577, 2025). "For instance, FoxO1 promoted TGF-β1 expression and liver fibrosis in a CCl4-induced mouse model." (PMID 40260391, 2025). "We then investigated whether macrophage Foxo1 influences STING activation and liver fibrosis in HFD-induced NASH." (PMID 39122845, 2024). "In summary, our data reveal a complex relationship between FOXO1, miR-183-5p, and the TGF-β signaling pathway, which might provide clues for the development of more effective strategies to treat cholestatic liver fibrosis." (PMID 34867446, 2021). "In conclusion, dietary BA enhanced the growth and alleviated liver fibrosis induced by a high starch diet to steatohepatitis/recovery symptom via improving glucose and lipid metabolism, which regulated by AKT/FOXO1 and cAMP/AMPK/SREBP1 pathway in largemouth bass." (PMID 31824338, 2019). "Conversely, the GHSR/Foxo1 axis promotes TGF-β1 secretion in macrophages via PKA-mediated phosphorylation of Foxo1 at S273, activating hepatic stellate cells and exacerbating inflammatory infiltration, thus aggravating carbon tetrachloride-induced liver fibrosis." (PMID 41459510, 2025). "In addition, another limitation of this study was the lack of a large number of liver fibrosis cases to further study the expression of miR-183-5p and FOXO1 and their correlation with pathological features." (PMID 34867446, 2021).
osteoporosis (28 papers, 2019 to 2026). A condition of reduced bone mass, with decreased cortical thickness and a decrease in the number and size of the trabeculae of cancellous bone (but normal chemical composition), resulting in increased fracture incidence. "This study provides an experimental and theoretical basis for further research on the mechanisms underlying age‐related osteoporosis, revealing that FoxO1 is a potential therapeutic target for the treatment of senile osteoporosis." (PMID 41363907, 2026). "Our study is aiming to detect the underlying mechanism of how AGE induces osteoporosis and the role of transcription factor FOXO1." (PMID 31886284, 2019). "Lastly, FOXO1A, Forkhead Box O1A, encodes a protein that is a member of the class O forkhead box family, proteins involved in bone cell function, which seems to be related to certain bone diseases such as osteoporosis or osteoatritis." (PMID 37175429, 2023). "Our study showed that FoxO1 responded to chronic oxidative stress induced by MACF1 deficiency to determine β‐catenin fate and regulate osteoblast differentiation during senile osteoporosis." (PMID 41363907, 2026). "More importantly, they revealed the regulatory effect of MACF1 on the FoxO1/β‐catenin pathway, osteoblast function, and mechanisms of aging‐related osteoporosis." (PMID 41363907, 2026). "The impaired functionality of FoxOs in bone cells contributes to osteoarthritis, osteoporosis, and other bone diseases, with FoxO1 and FoxO3 being extensively expressed and studied." (PMID 38987770, 2024). "The disruption of FOXO1 expression or its activity is known to contribute to numerous age-related diseases, such as OA, osteoporosis and muscle atrophy." (PMID 38092362, 2024). "AKT has also been reported to affect osteoporosis by upregulating FOXO1 and enhancing the expression of bone turnover markers (ALP, OCN, Runx2, and Col1) and extracellular matrix mineralization." (PMID 38260098, 2023). "circRNA_0006393 contributes to osteogenesis by targeting miR-145-5p/FOXO1 in glucocorticoid-induced osteoporosis." (PMID 35178103, 2022). "By searching the literature, we first confirmed that FOXO1 had a strong correlation with osteoporosis." (PMID 34777562, 2021). "We therefore concluded that FOXO1 expression was negatively correlated with osteoporosis progression." (PMID 34777562, 2021). "Hsa_circ_0006393 promotes osteogenesis by sponging miR-145-5p and upregulating FOXO1 in osteoporosis." (PMID 33648601, 2021). "The GAS5/SMAD7 axis and GAS5/miR-135a-5p/FOXO1 axis in MSCs are both involved in the development and prognosis of osteoporosis and will be described in greater detail in Section 4.1." (PMID 35155450, 2021). "Then, we used qRT-PCR to test the expression of miRNAs regulating FOXO1 predicted in PBMC of mice with osteoporosis and normal mice." (PMID 34777562, 2021). "Through literature searching, the osteoporosis-related gene FOXO1 in the key functional subset was determined to be the main object of the study." (PMID 34777562, 2021). "Meanwhile, many studies revealed that the upregulation of FOXO1 can restore the osteoblast viability of mice with osteoporosis." (PMID 34777562, 2021). "Based on the significance of FOXO1 in osteoporosis, we screened out 15 possible miRNAs regulating FOXO1 in miRNA-mRNA RegIN." (PMID 34777562, 2021). "To further predict the expression of the obtained miRNAs regulating FOXO1 in mice with osteoporosis, we firstly constructed a model of mice with osteoporosis." (PMID 34777562, 2021). "MiR-532-5p had a critical function in osteoporosis by regulating FOXO1 and osteoblast differentiation." (PMID 32404197, 2020). "In the present study, the functions of miR-532-5p in the regulation of osteoporosis were studied and its interactions with FOXO1 were also investigated." (PMID 32404197, 2020). "MiR-532-5p can provide references to osteoporosis by regulating the expression of FOXO1 and osteoblast differentiation." (PMID 32404197, 2020).
osteoporosis (continued). "This study revealed a critical role of FoxO1 in aging‐related osteoporosis." (PMID 41363907, 2026). "Collectively, these findings suggest that LYC attenuates osteoporotic bone loss through promoting osteogenesis and inhibiting adipogenesis via regulation of the FoxO1/PPARγ pathway driven by oxidative stress, presenting a novel strategy for osteoporosis management." (PMID 38794681, 2024). "Phewas analysis indicated that CPE and FOXO1 did not have genetic associations with any phenotypes other than osteoporosis." (PMID 39526243, 2024). "FOXO1 therefore plays an important role in the bone metabolism regulation of osteoporosis." (PMID 34777562, 2021). "Based on this conclusion, we speculated that osteoporosis-related miRNA biomarkers could be found in the miRNAs regulating FOXO1." (PMID 34777562, 2021). "Therefore, our results demonstrate that BN treatment suppresses osteoporosis via AKT/FOXO1 signaling pathway." (PMID 34198266, 2021). "Furthermore, it been shown that TNF-α inhibits Foxo1 by up-regulating miR-705, aggravating oxidative damage in BMSCs during osteoporosis." (PMID 33610167, 2021). "Resveratrol promotes osteogenesis via activating SIRT1/FoxO1 pathway in osteoporosis mice." (PMID 33708107, 2020). "Thus, it is possible that FOXO1 plays a crucial role in the pathogenesis development of DM-induced osteoporosis." (PMID 31886284, 2019). "Notably, miR‐142 could promote the osteoclastogenesis of bone marrow‐derived macrophages through targeting PTEN and modulating the PI3K/Akt/FoxO1 pathway, suggesting the involvement of miR‐142‐5p in osteoporosis." (PMID 32652747, 2020). "We identified DDIT4, FOXO1, and STAT3 as three central biomarkers that play pivotal roles in the pathogenesis of both osteoporosis and sarcopenia." (PMID 41282482, 2025). "Differential expression analysis in osteoporosis and sarcopenia datasets revealed that seven biomarkers—BCL6, DDIT4, FOXO1, IRS1, NFKBIA, PGK1, and STAT3—were differentially expressed in the independent osteoporosis dataset GSE84500." (PMID 41282482, 2025). "The expression of antioxidant-related proteins NRF2, HO-1, NQO1, FOXO1, and SOD-2 was increased to prevent advanced osteoporosis by inhibiting Aβ deposition and oxidative stress." (PMID 40153574, 2025). "Results revealed significant differential expressions of DDIT4, FOXO1, NFKBIA, PGK1, and STAT3 in the osteoporosis model." (PMID 41282482, 2025). "This study uncovers key molecular links between osteoporosis and sarcopenia, highlighting DDIT4, FOXO1, and STAT3 as shared biomarkers." (PMID 41282482, 2025). "To validate these findings, we examined gene expression across independent datasets and observed consistent differential expression of DDIT4, FOXO1, and STAT3 in both osteoporosis and sarcopenia cohorts, confirming their relevance as shared biomarkers." (PMID 41282482, 2025). "FOXO1, BMP4, WNT1, and EGFR in Cluster 2 are related to osteoporosis." (PMID 34777562, 2021). "In addition to its roles in the GAS5/SMAD7 and GAS5/miR-135a-5p/FOXO1 axes, GAS5 also had other regulatory effects in osteoporosis." (PMID 35155450, 2021). "In addition, glucocorticoid-induced osteoporosis in MC3T3-E1 cells was partially reversed by BN through inhibition of AKT, which, by upregulating FOXO1, enhanced expression of bone turnover markers (ALP, OCN, Runx2, and Col 1) and extracellular matrix mineralization." (PMID 34198266, 2021).
steatosis (28 papers, 2011 to 2025). Increased lipid within the cytoplasm of cells. "Macrophage Foxo1 deficiency (Foxo1M-KO) ameliorated hepatic inflammation, steatosis, and fibrosis, with reduced STING, TBK1, and NF-κB activation in HFD-challenged livers." (PMID 39122845, 2024). "Exposing the mice to HFD supplemented with cholesterol further exacerbates steatosis in FOXO1/3/4-deficient mice." (PMID 32660130, 2020). "Conversely, serum miRNAs associated with blunt steatosis specifically highlighted activity of FOXO1&HNF4α on CPT2, the lipid droplet and ER-lipid-raft associated PLIN3 and Erlin1." (PMID 27045805, 2016). "Moreover, FoxO1 is involved in metabolic regulation, and its dysfunction is linked to metabolic disorders associated with liver diseases, such as steatosis and NAFLD, thereby increasing the risk of fibrosis." (PMID 40076811, 2025). "We then used this dietary NASH model to determine whether myeloid FoxO1 deficiency would mitigate hepatic inflammation and stem the disease progress from steatosis to NASH." (PMID 35700043, 2022). "We propose a novel pathophysiological model of HFpEF in which suppression of the Xbp1s arm of the UPR blunts STUB1 expression, leading to the stabilization and overactivation of FoxO1 in cardiomyocytes with consequent cardiomyocyte steatosis and associated detrimental sequelae." (PMID 33727534, 2021). "The induction of Foxo1 and Plin2 was significantly stronger under steatosis compared to control conditions 20 h after synchronization." (PMID 38920666, 2024). "FoxO1 was upregulated in hepatic macrophages, correlating with hepatic inflammation, steatosis, and fibrosis in mice and patients with NASH." (PMID 35700043, 2022). "These clinical data indicate that human FOXO1 becomes deregulated in hepatic macrophages, correlating with the development of hepatic inflammation, steatosis, and fibrosis in patients with NASH." (PMID 35700043, 2022). "Here, we report that cardiomyocyte steatosis in HFpEF is coupled with increases in the activity of the transcription factor FoxO1 (Forkhead box protein O1)." (PMID 33727534, 2021). "The group treated with the FOXO1 inhibitor had slightly lower steatosis levels, but still exhibited some signs of macrovesicular steatosis." (PMID 32218743, 2020). "Steatosis was also improved in these animals, suggesting that Notch-induced steatosis was FOXO1-independent." (PMID 31615106, 2019). "We confirmed that ER stress-mediated hepatic steatosis is modulated by FoxO1 through insulin signaling in aged db/db mice." (PMID 31246177, 2019). "Deletion of FoxO1 in mouse liver results in steatosis while Akt2 deletion is protective for intracellular lipid accumulation that is induced by diet or Pten loss." (PMID 25502566, 2014). "The mechanism of Akt-dependent steatosis involves a number of down-stream effectors including GSK3β and FoxO1." (PMID 21479224, 2011). "To address the hypothesis that myeloid FoxO1 inhibition would suppress hepatic inflammation to prevent the progress of steatosis to NASH, we generated a NASH model by feeding C57BL/6 mice (male, 6 weeks old) a NASH-inducing diet." (PMID 35700043, 2022). "Thus, Notch signaling acted in an mTOR-dependent, FOXO1-independent manner to increase lipogenesis and steatosis." (PMID 31615106, 2019). "In addition, activation of the Sirt1-forkhead box O1 (FOXO1) signaling pathway by resveratrol inhibits the expression of SREBP-1 in a cell model of steatosis induced by palmitate." (PMID 22363635, 2012). "In general, we investigated the effects of FOXO1 in regulating steatosis-induced ER stress and necroptosis and our data indicate that FOXO1 does participate in the regulation of NAFLD and that the protein may be a potential therapeutic target in the treatment of NAFLD." (PMID 32218743, 2020). "When fed a NASH-inducing diet, myeloid cell FoxO1–knockout mice were protected from developing NASH, culminating in a reduction in hepatic inflammation, steatosis, and fibrosis." (PMID 35700043, 2022).
steatosis (continued). "Inactivation of FOXO1 and FOXO3 also results in hypertriglyceridemia and hypercholesterolemia due to increased hepatic lipid secretion and mild steatosis, indicating that FOXO1 and FOXO3 work together to inhibit critical pathways in adipogenesis as well as enhance gluconeogenic genes." (PMID 39618816, 2024). "SIRT1 may improve NAFLD by regulating ROS, PGC-1α, SREBP-1c, FoxO1/3, STAT3, and AMPK to restore mitochondrial function and reduce steatosis of the liver." (PMID 36008973, 2022). "On the other hand, livers of NASH patients exhibit a greater expression of FOXO1 compared to patients with simple steatosis as well as metabolically healthy patients with and without obesity." (PMID 32660130, 2020). "In the hepatocytes, miR-34a inhibit SIRT1, contributing to steatosis development via Sterol regulatory element binding proteins (SREBPs), Peroxisome proliferator-activated receptor-gamma coactivator-1 alpha (PGC-1α), Liver X Receptors (LRXs) and forkhead box protein O1 (FOXO-1)." (PMID 40943552, 2025).